IFNG (interferon gamma)
Diseases named in the same sentence as IFNG in open-access papers (continued):
Sharing a sentence is not in itself a finding about the gene and the disease.
infection (continued). "This is not, however, effective in promoting MAP clearance as the pathogen appears to block the sensitivity of infected cells to this key cytokine; pre-treatment of macrophages with IFNγ promotes their ability to clear mycobacteria while the same treatment is ineffective when given post-infection." (PMID 26664912, 2014). "At six weeks post-challenge, IFNG was up-regulated in animals that controlled infection." (PMID 24505407, 2014). "Based on the similar embryogenesis of female adult worms and comparable cytokine milieu at the site of infection, we concluded that the increased microfilaremia in ST2-ko mice is not primarily caused by differences in the production of Type 2 cytokines or IFNγ." (PMID 24663956, 2014). "In an immunocompetent host, once adequate cell-mediated immunity develops, the infection is eliminated by cytokines including interleukin-12 and interferon gamma that help “armed” macrophages in either killing the organism or halt its progression by forming a calcified granuloma." (PMID 25013413, 2014). "Next, we investigated whether there were changes in the cytokine milieu at the site of infection using the thoracic cavity lavage and assessed the levels of several cytokines: IL-4, IL-5, IL-13, IL-25, IL-33, and IFNγ." (PMID 24663956, 2014). "How neutrophils are recruited to secondary lymphoid organs is unknown; however, IFNγ has been shown to mediate neutrophil recruitment to the lung following tissue injury or infection." (PMID 25010693, 2014). "However, IFNγ serum levels from the mice 5 days post infection were identical between SB505124 and vehicle-control treated mice." (PMID 24945800, 2014). "The position of these IL17-producing memory T cells within the lungs meant they were able to respond quickly when stimulated by antigen and produce IL17, leading to the recruitment of antigen-specific IFNG-producing T cells from the central lymphoid tissue back to the site of infection." (PMID 24505407, 2014). "Therefore, the production of IFNγ, TNFα and IL-17 following immunization coincided with strong protection against infection, potentially due to a synergistic interaction between multiple pro-inflammatory cytokines." (PMID 23613984, 2013). "Lung IFNγ levels were highly elevated in mice deficient for both IL-1α and IL-1β or for IL-1R1 at 5 weeks after M. tuberculosis infection, reminiscent of TNF deficient mice at 4 weeks, when they succumb to infection." (PMID 25400917, 2013). "Exposure to Mtb induces severe infections to individuals defective in IFNγ or IFNγ receptor gene." (PMID 24350246, 2013). "We hypothesize that this SIV related IFNγ down-modulation may play a role in the suppressed immune activation observed during the chronic phase of the infection in mangabeys compared to SIV infected macaques and HIV-infected humans." (PMID 23825945, 2013). "However, in the absence of IL-17, immunization protocols that protect WT mice against infection and inflammation are ineffective due to the greatly reduced production of IFNγ and protective Th1 immunity." (PMID 24073293, 2013). "One of the 4 selected antigens is the DO serine protease HtrA, which is particularly unique in that it induces both high antibody titres and IFNγ+/CD4+ T cells during natural infection in human beings (Grifantini, personal communication) and during experimental infection in mice." (PMID 24009891, 2013). "Following infection, Lm promptly triggers a series of innate immune cell activation where IFNγ produced mainly by natural killer (NK) cells contributes to initial resistance then triggers the induction of TNF-α and iNOS-producing dendritic cells (Tip-DC) that can control bacterial growth in vivo." (PMID 24068935, 2013).
infection (continued). "In contrast, cVac infection of HBV transgenic mice triggered IFNγ (black bar) and Granzyme B (black bar) expression by a small but significant fraction of the transferred intrahepatic COR93-specific CD8+ T cells without significantly increasing their expansion in the liver (black bars)." (PMID 23853599, 2013). "We next asked whether pre-infection could also enhance IFNγ-induced STAT1 binding to labeled gamma-activated sequence (GAS) oligonucleotides from the Irf-1 promoter in an electrophoretic mobility shift assay (EMSA)." (PMID 23527309, 2013). "With respect to immunity to infection, we have previously reported that increased resistance to the helminth parasite Schistosoma mansoni following drug treatment and IL-10R blockade led to elevated antigen-specific IFNγ, IL-5 and IL-17A production." (PMID 23345540, 2013). "On the other hand, antigen-experienced γδ T cells produce IFNγ at the site of infection." (PMID 23704936, 2013). "Our prior studies found that SMARTA effector cells generated following Lm-gp61 infection demonstrated poor function as measured by the frequency of responders able to produce IFNγ, IL-2 and TNFα simultaneously upon restimulation and the amount of cytokine produced on a per cell basis." (PMID 23840678, 2013). "However, our findings with IFNγ−/− neonatal mice show that during the infection CXCL9 and CXCL10 upregulation was strongly IFNγ-dependent." (PMID 24367259, 2013). "In contrast, IFNγ, the only type II interferon, is synthesized by cells of the immune system upon their recruitment to infected cells, which takes place days or even weeks after infection." (PMID 23383295, 2013). "Our previous studies in mice infected with Leishmania major revealed that early in infection, the infected dermis contained an IL-4-dominant immune infiltrate that was in contrast to the generation of a mixed IL-4 and IFNγ anti-Leishmania response in the draining lymph node." (PMID 23991011, 2013). "Thus, the diminution of plasma IFNγ in mice challenged with bacteria and IL4I1 probably reflects the reduced inflammation associated with the control of the infection." (PMID 23355881, 2013). "A combined effect of the genotypes associated with increased risk of PTB (i.e. TLR9 1174G/G and IFNG 2109 A/A) was found when comparing PTB patients with LTBI controls (p=0.004) but not with healthy controls without infection (p=0.433)." (PMID 24176007, 2013). "In contrast, we found that pDC deficiency resulted in higher IFNγ production in the lungs in the adaptive immune phase following infection, although we did not analyse at early stage of infection." (PMID 24386207, 2013). "Interestingly, those patients who developed a second infection or died had significantly less IFNγ secretion from in vitro stimulated PBMCs than those who recovered uneventfully." (PMID 22742734, 2012). "Therefore, in these studies, we used non-myeloid MEFs as a model for epithelial cells to understand how IFNγ enables the host to control, and finally clear, an infection with this pathogen." (PMID 22912573, 2012). "In this malarial model, all the pro-inflammatory cytokines, TNFα, IFNγ, IL-1, IL-6 and IL-18 and the anti-inflammatory cytokine IL-10, were significantly elevated in the plasma throughout the infection with the highest level recorded during the late critical stage." (PMID 23323093, 2012). "Hence, the requirement for CD11c+ cells to maintain T cell IFNγ production would appear to be context and/or infection-specific." (PMID 22911108, 2012). "Additionally, we have found that T1IFNs regulate gene expression and contribute to control of infection in a manner that is largely redundant with IFNG signaling." (PMID 23144737, 2012). "However, as the infection evolves, activated T cells produce large amounts of IFNγ, which lead to a change in the actions of MSCs and activation of their antiinflammatory properties." (PMID 22815907, 2012).
infection (continued). "Impaired secretion of IFNγ correlated with death or development of secondary infection." (PMID 22742734, 2012). "The capacity for cDCs to drive polarization of IFNγ+IL-10+ cells may be as a result of their higher expression of IL-27 than CD11cint cells during infection." (PMID 22911108, 2012). "Thus, mice infected with Lm were unable to mount a full NK cell response, in terms of IFNγ production, during the very early stages of infection." (PMID 22912878, 2012). "As IFNγ-driven Th1 immune responses are considered necessary for protection againstMTB infection, we tested whether spleen cells from helminth co-infected cotton ratsproduce less IFNγ in response to PPD compared to cells from MTB-infected controls." (PMID 23285308, 2012). "We found that the main sources of IFNγ under infection were CD11c+ and CD68+ cells." (PMID 22815907, 2012). "Since we observed higher levels of phospho-STAT1Tyr in infected cells as compared to uninfected cells after IFNγ stimulation, we wondered whether infection with type I, II, or III parasites induces nuclear phospho-STAT1Tyr in the absence of IFNγ." (PMID 23240025, 2012). "Release of IL-12 by macrophages and dendritic cells could therefore promote NK cell-mediated production of IFNγ during the early phase of infection, while IL-2 from T cells provides a potential stimulus for activation of NK cells at later stages." (PMID 22788220, 2012). "Furthermore, immunocompetent mice challenged with 105 CFU of S. flexneri were able to clear the infection by 5 days post infection, while IFNγ−/− mice were unable to inhibit S. flexneri replication and eventually succumbed to the infection." (PMID 22912573, 2012). "After three hours of infection, with IFNγ stimulation for the last two hours, cells pre-infected with either RH(I), Pru(II), or CEP(III) all had significantly lower levels of IRF1 in their nuclei than uninfected cells, as was previously seen for type I, II, and III strains." (PMID 23240025, 2012). "Moreover, sporozoite specific IFNγ response by hepatic CD8+CD44hi T cells was boosted by each challenge infection." (PMID 22563506, 2012). "Moreover, in the chronic phase of infection (120 dpi) the accumulation of CD8+ H-2Kb/VNHRFTLV+ IFNγ+ cells in spleen was confirmed." (PMID 22532799, 2012). "Despite a decrease in systemic IFNγ production after i.p. challenge, Pilrb deficient mice had no issue clearing the parasite from the local site of infection." (PMID 22479310, 2012). "In addition, the inhibitory effect of sand fly saliva on macrophage antigen presentation and interferon gamma (IFN-γ) activation enables successful infection establishment." (PMID 26623300, 2012). "It is possible that during human infection this delay is sufficient for S. flexneri to begin its cycle of replication and cell-to-cell dissemination prior to being killed by IFNγ-induced mechanisms, further pushing the host-pathogen balance in favor of the bacteria." (PMID 22912573, 2012). "Similarly to the observed effects in the spleen, IFNγ expression was 2.3-fold increased in the heart of the MSC-treated infected mice on the 7th day after infection compared to the PBS-treated infected mice (p = 0.03)." (PMID 22815907, 2012). "Mice with dominant negative MAML (DNMAML) protein preventing the canonical transcriptional activation by all four Notch receptors were previously reported to be able to control infection with L. major and to have normal levels of IFNγ in their dLN CD4+ T cells." (PMID 22396647, 2012). "Interestingly, S. flexneri-mediated induction of IFNβ secretion was dependent on RIG-I if the MEFs were stimulated with IFNγ prior to the infection." (PMID 22912573, 2012). "However our data are in contrast to a report showing that CD11c-depletion during established infection with S. mansoni resulted in a significant reduction in IFNγ+ production by CD4+ T cells after ablation of CD11c-expressing cells." (PMID 22911108, 2012).
infection (continued). "Therefore, the ratio of IFNγ+ to Pfn+ cells decreased and resulted in a relative enrichment of Pfn+ cells among the inflammatory cells that invaded the cardiac tissue as the infection approached the chronic phase." (PMID 22532799, 2012). "However, when J774A.1 macrophages were primed with IFNγ prior to infection, they differentiated to a CAM phenotype and the spread to Hep-2 cells was significantly reduced compared to cells that were not primed." (PMID 22792355, 2012). "WT mice produced more IFNγ and IL-10 mRNA at the infection site 2 weeks after L. major infection." (PMID 22007288, 2012). "Among the other tested pro-inflammatory cytokines including TNFα1, TNFα2 and IFNγ, none appeared consistently induced by the infection either in micro-arrays or in QPCR, underlining the primary implication of IL1β in pronephros at this stage of the infection." (PMID 22720048, 2012). "Furthermore, infection of macrophages and DCs with Lm causes IFN-I dependent downregulation of the IFNγ-receptor, hence unresponsiveness to IFNγ." (PMID 22719255, 2012). "Most of the peptides induced IFNγ-producing cells at one or more time points post infection." (PMID 22384112, 2012). "Not surprisingly, because cardiomyocytes do not express Slamf1, upon infection with T. cruzi these cells, whether isolated from wt or Slamf1−/− BALB/c mice, produced equal amounts of IFNγ and nitric oxide (NO) upon in vitro infection." (PMID 22807679, 2012). "After eighteen hours of infection cells were treated with IFNα or IFNγ or left untreated." (PMID 22163042, 2011). "IRF8−/− mice do not produce IL-12p40, lack Th1 polarization (absence of antigen specific CD4+, IFNγ producing T cells), and are susceptible to in vivo infection with intracellular pathogens." (PMID 21731497, 2011). "We observed that IFNγ-induced STAT1 phosphorylation was blocked similarly by both isolates at all times post infection, whereas IFNα-induced STAT1/2 phosphorylation was dependent the degree of growth of the virus, the block developing more slowly in cells infected with the slower-growing GV isolate." (PMID 22163042, 2011). "These cytokines were also studied 7 days post infection and it was observed that mice from infection control group (S) and the group fed continuously with the probiotic strain maintained increased expression of both TNFα and IFNγ in the cells isolated from Peyer's patches." (PMID 21813005, 2011). "Consequently, it appears that healing and resolution of infection is dependent upon effector CD8 T cells; overall activation of CD8 T cells results in lower levels of IL-13 and IL-10 as well as IFNγ produced in response to infection." (PMID 21695103, 2011). "Thus, in response to inflammatory signals elicited during acute infection, HSCs can undergo a rapid, IFNγ-dependent, transient shift from dormancy to activity, ostensibly, to provide the host with additional or better-armed innate cells for host defense." (PMID 22194881, 2011). "Survival of M. avium within phago-lysosomes of macrophages may be explained by reduced response to interferon gamma (IFNG) upon infection." (PMID 21629653, 2011). "Adult immunocompetent mice clear the infection without pathogenic consequences, chiefly via interferon gamma (IFN-γ)." (PMID 22216008, 2011). "To assess immune responses during vaccination and infection, we measured antigen-specific antibody isotype titres as a surrogate of the underlying CD4+ T cell response, given the known correlation between IL-4 and IgG1 responses and between IFNγ and IgG2a." (PMID 22216363, 2011). "Contrary to BCG, on extending the time of evaluation to 16 weeks post-infection, rBCG vaccination resulted in a considerable decline in the levels of IFNγ and IL10; a significant increment in the levels of IL12 (p<0.05), while the levels of TNFα and TGFβ remained unaltered." (PMID 21533158, 2011). "Interferon gamma is a key cytokine coordinating immune defense against infection." (PMID 21829463, 2011).
infection (continued). "With increasing time of infection at 12 hr post infection, we observed a sharp decline in the percentage of the colocalized IFNγR1 (32.7%) along with absolute failure of IFNγ to induce any detectable increase in the colocalization pattern at this condition (34.2%)." (PMID 21931549, 2011). "Indeed, MyD88 deficiency resulted in complete abrogation of IFNγ production by CD4+ T-cells and an inability to control infection." (PMID 21253574, 2011). "In our model, the number of IFNγ (+) cells in small intestinal tissues was significantly lower in the group of mice from the infection control group (S) than in the group of mice given continuously L. casei CRL 431, which maintained the number of these positive cells similar to the Lc group." (PMID 21813005, 2011). "Unexpectedly, TLR2/4 double-deficient but not TLR2-deficient mice displayed upon infection with the microorganism significantly higher pulmonary levels of IFNγ than wild type mice." (PMID 22096480, 2011). "IFNγ signaling has been considered to be detrimental during chronic infection, but we propose that IFNγ signaling is essential for activating the hematopoietic response to infection, and for the production of innate immune cells required for combating infection." (PMID 22194881, 2011). "It is required for ontogeny and maturation of macrophages and dendritic cells, for activation of anti-microbial defenses, and for production of the Th1-polarizing cytokine interleukin-12 (IL-12) in response to interferon gamma (IFNγ) and protection against infection with Mycobacterium tuberculosis." (PMID 21731497, 2011). "For 9/14 of the epitopes where mutations confirmed to confer escape were selected in acute/early infection, we measured T cell recognition of both the index sequence and variant epitope peptides at time-points over the first year of infection by IFNγ ELISPOT assay." (PMID 21635736, 2011). "A study in Myd88-/- mice infected with L. major has highlighted the importance of TLRs, IL-1 and/or IL-18 in the induction of IL-12 and the generation of Th1 responses; MyD88 deficiency also resulted in complete abrogation of IFNγ production by CD4+ T cells and an inability to control infection." (PMID 21253574, 2011). "However, many other cytokines can do so, too and multiple signals, including IL-22 and IFNγ, will drive tissue inflammation in a redundant fashion during the course of a real infection." (PMID 21124903, 2010). "Analysis of mucosal immunity to C. jejuni allows us to hypothesise a critical role for IFNγ in particular, during the early, acute phase of infection." (PMID 21085698, 2010). "Moreover, in individuals with DENV1 infection, the IFNα elevation appears early, followed by the induction of a pro-inflammatory cytokine IFNγ, and lastly an anti-inflammatory cytokine IL-10." (PMID 21206915, 2010). "IFNγ also has antiviral properties, however, suppression of IFNγ signaling may also modulate adaptive immune responses to infection." (PMID 20084112, 2010). "For instance, depleting immunocompetent mice of TNFα, IFNγ, or neutrophils renders them much more susceptible to infection with LVS, but not to virulent subsp." (PMID 20967278, 2010). "The most significant changes correlating with the severity of infection were observed in NK cells that could result in the reduced production of pro-inflammatory IFNγ and immunosuppressive IL-10." (PMID 20226037, 2010). "Both innate and adaptive T cell-immunity to C. jejuni infection led to the release of IFNγ, IL-22 and IL-17A; suggesting a critical role for this cytokine triad in establishing host anti-microbial immunity during the acute and effectors phase of infection." (PMID 21085698, 2010). "IFNγ production by the innate arm of the immune system produces a rapid response that may be key in controlling the early stages of infection." (PMID 21048923, 2010).